PDCD1 (programmed cell death 1)
Diseases named in the same sentence as PDCD1 in open-access papers (continued):
Sharing a sentence is not in itself a finding about the gene and the disease.
cervical carcinoma (21 papers, 2015 to 2025). A carcinoma arising from either the exocervical squamous epithelium or the endocervical glandular epithelium. "It was reported that a prognostic signature consisting of immune-related long non-coding RNAs, such as CTLA-4, PDCD1, and so on, correspondingly predicted risk of cervical cancer and responded to cervical cancer patients’ immunotherapy of mitomycin C and chemotherapeutics of axitinib and docetaxel." (PMID 36536343, 2022). "Camrelizumab is a humanized high-affinity IgG4-kappa monoclonal antibody targeting programmed cell death 1 (PD-1), which has been progressively documented as a therapy for advanced cervical cancer with good result metrics." (PMID 39777331, 2024). "Cancer cells employ programmed cell death ligand-1 (PD-L1), an immune checkpoint protein that binds to programmed cell death-1 (PD-1) and is highly expressed in various cancers, including cervical carcinoma, to abolish T-cell-mediated immunosurveillance." (PMID 34577118, 2021). "The upregulation of signaling through negative co-stimulatory molecules on T cells, such as Cytotoxic T-lymphocyte Antigen 4 (CTLA-4) and programmed cell death-1 (PD-1), is another mechanism through which T-cell infiltration and function can be impaired in cervical cancer." (PMID 28344877, 2017). "In cervical cancer patients, we found CSCC cohorts obtained higher TMB score, MSI score and common inhibitory checkpoints expression (e.g., PDCD1, CD274, BTLA, CTLA4, TIGIT, etc.), accompanied by more abundant immunocytes infiltration." (PMID 38206304, 2024). "Approximately 78% of cervical cancers (CCs) (228/293) were identified to show significant enrichment in immune cells (e.g., CD8 T cells and macrophages), a type I IFN response, enhanced cytolytic activity and high PDCD1, and these CCs were referred to as the “immune class”." (PMID 33971902, 2021).
liver cancer (21 papers, 2021 to 2026). An epithelial or non-epithelial malignant neoplasm that arises from the liver. "These research preclinical findings back up the exploration of TIM3, LAG-3, and PDCD1 inhibition in liver cancer cases." (PMID 38248311, 2023). "In order to identify novel immune biomarkers from the TCGA-LIHC and examine associated expression with established immune biomarkers for T cell activation with an immune checkpoint inhibitor in liver cancer, this study examined PDCD1, CTLA4, HAVCR2, and LAG3." (PMID 38248311, 2023). "In recent years, several key clinical trials have evaluated the use of locoregional transarterial chemotherapy combined with immune checkpoint inhibitors, such as programmed cell death-1 (PD-1) and programmed cell death-ligand 1 (PD-L1) inhibitors, in liver cancer." (PMID 39246324, 2024). "At the same time, studies have shown that immunotherapy with anti PDCD1 and anti CTLA-4 antibodies is effective in the treatment of advanced liver cancer." (PMID 37081394, 2023). "An analysis of single-cell sequencing data of liver cancer immune cells found that lncRNA MIAT was significantly enriched in Foxp3+ CD4+ T cells, PDCD1+ CD8+ and GZMK+ CD8+ T cells, which mediated the immune escape of liver cancer." (PMID 36092924, 2022). "The mRNA expression levels of immune checkpoint-related genes were significantly higher in the high-risk group than in the low-risk group, especially for immune checkpoint-related genes commonly used in liver cancer immunotherapy, including (PD-L1, PDCD1LG2, PDCD1, TIGIT, TIM-3, CTLA4)." (PMID 36814910, 2023).
rheumatoid arthritis (21 papers, 2006 to 2025). A chronic, systemic autoimmune disorder characterized by inflammation in the synovial membranes and articular surfaces. "Several studies investigated the relationship between programmed cell death 1 (PDCD1) gene polymorphisms and rheumatoid arthritis (RA) risk, but the results were controversial." (PMID 28858091, 2017). "Genes involved in regulating peripheral tolerance were found have effects on the development of RA, such as PTPN22 C1858T (rs2476601), CTLA-4 A49G, and PDCD-1 (rs36084323), and PD-L1 6777G was associated with the prevalence of rheumatoid nodules." (PMID 28969061, 2017). "The strongest evidence is for PDCD1, which meets all five criteria: nearby GWAS hit, protein association, Mendelian randomization support, validation from perturbation in an experimental model, and effects of a targeted agonist against rheumatoid arthritis in a phase 2 trial." (PMID 39887658, 2025). "For two putative core genes—CTLA4 and PDCD1—there is at least preliminary evidence of efficacy against rheumatoid arthritis in clinical trials of drugs that target the protein." (PMID 39887658, 2025). "For five of the 16 putative core genes—CD5, CTLA4, SLAMF1, PDCD1, and TNFRSF14—that were identified through association of GATE scores with rheumatoid arthritis, associations of rheumatoid arthritis with SNPs within 200 kb of the transcription site are listed in the GWAS catalog." (PMID 39887658, 2025). "PDCD1 has also been associated with SLE and Rheumatoid Arthritis (RA)." (PMID 18045485, 2007).
esophageal cancer (20 papers, 2020 to 2025). A primary or metastatic malignant neoplasm involving the esophagus. "As for particular types of gastrointestinal cancer, according to our best knowledge, in the literature there are only three studies aimed at investigating the PDCD1 SNPs as potential risk factors for esophageal cancer, more precisely esophageal squamous cell carcinoma (ESCC)." (PMID 33519815, 2020). "Tislelizumab, a humanized IgG4 anti-programmed cell death 1 (PD-1) monoclonal antibody approved in China in 2019 for advanced solid tumors such as esophageal cancer, functions by blocking the PD-1/PD-L1 pathway to reactivate anti-tumor immunity." (PMID 41268547, 2025). "Sintilimab, a programmed cell death-1 (PD-1) inhibitor, has been approved for various cancers in China, including esophageal cancer." (PMID 39351355, 2024). "Immune checkpoint inhibitor (ICI) therapies have been evaluated for their effect on specific microbes in esophageal cancer, including cytotoxic T lymphocyte-associated protein 4 (CTLA-4) and programmed cell death 1 (PD-1)/PD-1 ligand (PD-L1) inhibitors." (PMID 36845103, 2023). "Nivolumab and pembrolizumab, antibodies blocking the programmed cell death 1 (PD-1) receptor on T cells, have recently gained approval for clinical use in esophageal cancer patients for specific indications." (PMID 35836094, 2023). "Clinically, there are two main immunotherapy options for patients with esophageal cancer, namely, anti‐programmed cell death 1 (anti‐PD‐1)/anti‐programmed cell death 1 ligand 1 (anti‐PD‐L1) and anti‐cytotoxic T‐lymphocyte‐associated antigen‐4 (anti‐CTLA‐4) therapy." (PMID 37199321, 2023). "In the TISIDB database, ENTPD1 expression in esophageal carcinoma was shown to be statistically positively correlated with the expression of currently recognized inhibitory immune checkpoint molecules PDCD1 (p < 0.001), CTLA4 (p < 0.001), and HAVCR2 (p < 0.001)." (PMID 36831526, 2023). "Furthermore, Kaplan-Meier survival curves showed higher PDCD-1 gene expression contributed to worse survival of esophageal cancer patients." (PMID 34829753, 2021). "Of the five cancers that demonstrated a significant role for PDCD1 in patient survival, esophageal cancer stood out with low PDCD1 expression being beneficial for the patient cohort, whereas the other four cancers all showed high PDCD1 expression to be beneficial." (PMID 34067485, 2021). "These potential differences could go some way to explaining the differing role that PDCD1 expression has on patient survival, given that esophageal cancer was distinct from the other four cancers in that low PDCD1 was beneficial for esophageal cancer patients." (PMID 34067485, 2021). "Moreover, we found that the expression level of ENTPD1 was positively correlated with the infiltrating abundance of CD8+ T cells and the expression level of inhibitory immune checkpoint molecules PDCD1, CTLA4, and HAVCR2 in esophageal carcinoma, but not in normal tissues." (PMID 36831526, 2023).
type 1 diabetes (18 papers, 2007 to 2026). "Immune checkpoint inhibitor–induced type 1 diabetes mellitus (ICI-T1DM) is a rare but serious immune-related adverse event associated with programmed cell death-1 inhibitors such as nivolumab." (PMID 40696648, 2025). "We genotyped two PDCD1 SNPs (7146G>A and 872C>T), which have previously been associated with type 1 diabetes and RA respectively." (PMID 18045485, 2007). "We found some evidence of associations between type 1 diabetes and TAF5L, PDCD1, TCF7 and IL6 (ORs = 1.05 – 1.13; P = 0.0291 – 4.16 × 10-4)." (PMID 18045485, 2007). "Although TAF5L (C744A; rs3753886), PDCD1 (7146G>A; rs11568821), TCF7 (C883A; rs5742913) and IL6 (IL6-174G>C; rs1800795) have previously been associated with type 1 diabetes, the possibility remains that these associations are false positives." (PMID 18045485, 2007). "Consequently, additional studies will be required to ascertain the contribution of TAF5L, PDCD1, TCF7 and IL6 to type 1 diabetes susceptibility." (PMID 18045485, 2007). "Programmed cell death 1 antibodies have been generally confirmed to be less toxic than conventional cytotoxic chemotherapy, although unusual immune-related adverse events such as type I diabetes mellitus, adrenal failure, and myasthenia gravis may occur with a very low incidence." (PMID 31647029, 2019). "TAF5L, PDCD1, TCF7, IL6 and ICAM1 may be amongst the numerous loci with small effects in type 1 diabetes." (PMID 18045485, 2007).
urothelial carcinoma (18 papers, 2019 to 2025). A malignant neoplasm derived from the transitional epithelium of the urinary tract (urinary bladder, ureter, urethra, or renal pelvis). "Immune checkpoints, such as programmed cell death-1 (PD-1) and its associated ligand (PD-L1), have attracted significant attention as major protein targets for systemic immunotherapy of a number of solid tumors, including urothelial carcinoma (UC)." (PMID 33134169, 2020). "Immune checkpoint inhibitors (ICIs) can enhance the anti-tumor immune reaction of T cells by targeting cytotoxic T lymphocyte antigen-4 (CTLA-4), and programmed cell death 1 (PD-1) or its ligand (PD-L1), and have been extensively applied for various tumors, including urothelial carcinoma." (PMID 34867321, 2021).
lung adenocarcinoma (17 papers, 2017 to 2025). A carcinoma that arises from the lung and is characterized by the presence of malignant glandular epithelial cells. "Target transcripts for immune checkpoint molecules such as PD-1/PD-L1 and (programmed cell death-1/its ligand and cytotoxic T-lymphocyte antigen 4) have proven to be beneficial against several solid tumors, including lung adenocarcinoma." (PMID 29176936, 2017). "Moreover, the SUMO-C1 group showed a higher expression of co-stimulatory and MHC molecules and lower expression of co-inhibitory molecules, such as CD274, PDCD1, and LAG3, which are now commonly used as immunotherapeutic checkpoints in lung adenocarcinoma." (PMID 37123398, 2023).
multiple myeloma (16 papers, 2018 to 2026). "The potential association of PDCD1 polymorphisms with hematological malignancies was evaluated in several studies including multiple myeloma and leukemia." (PMID 33519815, 2020). "Several studies have assessed the potential link between PDCD1 gene variations and hematological cancers such as multiple myeloma and leukemia." (PMID 38792904, 2024). "CD8-COTL1 exhausted T cell expressed higher immune checkpoint PDCD1, especially in myeloma microenvironment with high tumor infiltration." (PMID 36532059, 2022). "Despite the impressive clinical impact of programmed death-ligand 1 (PD-L1)/programmed cell death-1 (PD-1) blockade in solid tumors, the use of these checkpoint inhibitors in multiple myeloma (MM) still remains debated with unsatisfying clinically meaningful results." (PMID 33418913, 2021).
endometrial cancer (15 papers, 2018 to 2025). Primary or metastatic malignant neoplasm involving the endometrium (mucous membrane that lines the endometrial cavity). "Why the high-risk AS events in PDCD1 lead to a worse prognosis of endometrial cancer needs further study." (PMID 35836577, 2022). "First, we included the expression profile data of all normal endometrial samples and endometrial cancer samples of TCGA and observed the expression levels of common immune checkpoints, including PDCD1, CD274 (PDL1), PDCD1LG2 (PDL2), CTLA4, LAG3, and HAVCR2." (PMID 37872211, 2023). "Pembrolizumab, a monoclonal antibody targeting programmed cell death 1(PD-1), was approved for the second-line treatment of metastatic or recurrent endometrial cancer with microsatellite instability-high (MSI-H) or mismatch repair-deficient (dMMR) status." (PMID 35619813, 2022). "Multiple ICIs against programmed cell death-1 (PD-1), programmed death-ligand 1 (PD-L1), and cytotoxic T lymphocyte-associated antigen 4 (CTLA-4) have demonstrated encouraging outcomes in controlled clinical studies for advanced cervical and endometrial cancers." (PMID 39050882, 2024). "Through our analysis of the TCGA dataset, we discovered that in Uterine Corpus Endometrial Carcinoma (UCEC) samples, the expression level of SLC2A1 was negatively correlated with the expression levels of CD96, CTLA-4, and PDCD-1." (PMID 40746529, 2025).
Obesity (14 papers, 2019 to 2024). Accumulation of substantial excess body fat. "This study was conducted to assess the expression of Fas (CD95) and programmed cell death-1 (PD-1) on circulating T-cells in obesity using a diet-induced obesity mouse model." (PMID 33808960, 2021). "To further explore whether AT T cells contain an exhausted signature following obesity, we generated an exhaustion module containing multiple established gene expression features of T cell exhaustion: Pdcd1, Tox, Entpd1, Tigit, and Lag331,32." (PMID 35618862, 2022). "On the contrary, obesity-associated mechanisms can alter the function of CD8+ T cells and neutralize their anti-tumorigenic potential through multiple mechanisms involving PD-L1 and programmed cell death 1 (PD-1)." (PMID 34944905, 2021).
osteosarcoma (14 papers, 2021 to 2025). A usually aggressive malignant bone-forming mesenchymal neoplasm, predominantly affecting adolescents and young adults. "This study found that macrophage M1 was positively correlated with immune checkpoints PDCD1, CD274 (PD-L1), PDCD1LG2, CTLA4, and TIGIT, suggesting the opportunity of ICBs therapy in osteosarcoma patients with high infiltrating macrophage M1." (PMID 34335756, 2021). "Beside these, we do not see any significant correlation between expression levels of CD274 and PDCD1LG2 genes, that encodes PD-L1 and PD-L2 respectively, with the expression levels of PDCD1 and IFNG, and the percentage of CD8 T cells in osteosarcoma tumors." (PMID 33757216, 2021).
renal carcinoma (14 papers, 2018 to 2025). A carcinoma arising from the epithelium of the renal parenchyma or the renal pelvis. "In a separate study involving renal cancer patients treated with nivolumab, the effect of three PDCD1 SNPs (PD1.3, PD1.5, and PD1.6) on irAEs was assessed." (PMID 41244914, 2025). "The immunohistochemical data from HPA showed that EOMES and PDCD1 exhibited medium staining in the cytoplasm and cytomembrane of the tumor cells in the renal cancer." (PMID 34531849, 2021). "ICIs, including antibodies targeting programmed cell death 1 (PD1) and programmed cell death ligand 1 (PD‐L1), have demonstrated effectiveness against diverse cancers, such as melanoma, non‐small‐cell lung cancer, and renal cancer." (PMID 38594879, 2024).
esophageal squamous cell carcinoma (13 papers, 2020 to 2025). Esophageal squamous cell carcinoma (ESCC) is a type of esophageal carcinoma (EC) that can affect any part of the esophagus, but is usually located in the upper or middle third. "Histopathology of the excised specimen was positive for programmed cell death 1, programmed cell death ligand-1, New York esophageal squamous cell carcinoma-1, and melanoma-associated antigen 4; their expression may be a therapeutic target for cAS." (PMID 35839046, 2022). "Here, we aimed to rewrite the PDCD1 locus to express IL-12 instead of PD-1 in New York esophageal squamous cell carcinoma 1 (NY-ESO-1)-specific T cells." (PMID 36793716, 2023). "B cells and B cell-related gene signatures in the tumor microenvironment (TME) are associated with the efficacy of anti-programmed cell death-1 (anti-PD-1) therapy in several cancer types, but not known for esophageal squamous cell carcinoma (ESCC)." (PMID 35847892, 2022).
kidney cancer (13 papers, 2019 to 2026). Primary or metastatic malignant neoplasm involving the kidney. "Kidney cancer is a highly immunogenic tumor in which the tumor cells produce an immunosuppressive environment through a variety of mechanisms, such as increased expression of immunosuppressive molecules(PDCD1, CD274, CTLA4) in the TME and the occurrence of immune escape." (PMID 35860566, 2022). "Higher expression of LAG3, PDCD1, and TIGIT showed the worst survival outcome of anti-ICB therapy in kidney cancer indication drug resistance, whereas high LAG3 and CXCL13 expressions were associated with better survival of anti-PDL1 therapy in metastatic BLCA, indicating drug sensitivity." (PMID 40076932, 2025).
small cell lung carcinoma (13 papers, 2018 to 2024). Small cell lung cancer (SCLC) is a highly aggressive malignant neoplasm, accounting for 10-15% of lung cancer cases, characterized byrapid growth, and early metastasis. "Immune checkpoint inhibitors (CPIs) including anti-programmed cell death 1 (PD-1), anti-PD ligand 1 (PD-L1) and anti-cytotoxic lymphocyte associated protein 4 (CTLA-4) antibodies have shown promising results in several solid cancers including small cell lung cancers." (PMID 29986769, 2018). "Anti–programmed cell death 1 (PD1) and anti-programmed death ligand 1 (PD-L1) monoclonal antibody checkpoint inhibitors are increasingly used in the adjuvant therapy of small cell lung cancer." (PMID 36461029, 2022).
metastatic colorectal cancer (12 papers, 2019 to 2025). "Pembrolizumab is a monoclonal antibody to programmed cell death 1 protein and FDA approved as second-line therapy for unresectable metastatic colorectal cancer that has high microsatellite instability or deficient mismatch repair." (PMID 31675944, 2019).
sarcoma (12 papers, 2017 to 2023). A usually aggressive malignant neoplasm of the soft tissue or bone. "Immune checkpoint inhibitors (ICIs) targeting programmed cell death-1 (PD-1) and its corresponding ligand PD-L1 are being increasingly used for a wide variety of cancers, including refractory sarcomas." (PMID 37325672, 2023). "In order to explore the potential of immune checkpoint blockade in sarcoma, we investigated expression and clinical relevance of programmed cell death-1 (PD-1), programmed death ligand-1 (PD-L1) and CD8 in tumors of 208 sarcoma patients." (PMID 29050367, 2017). "Given the strong correlation between PDCD1 and CD8A in the TCGA sarcoma cohort, the next analysis addressed whether PD1+ cells harbored a similar prognostic potential as CD8+ cells in combination with CD11c+ cells." (PMID 33803245, 2021). "Finally, the results of immune checkpoints’ expression showed significant differences in CD274, HAVCR2, PDCD1, and TIGIT between the two subtypes, and m7GRGs might be a predictive marker for the treatment of sarcomas by targeting immune checkpoints." (PMID 36816047, 2023).